EGFR (epidermal growth factor receptor)
Diseases named in the same sentence as EGFR in open-access papers (continued):
Sharing a sentence is not in itself a finding about the gene and the disease.
tumor (continued). "Notably, CD8T_GNLY+ in tumor samples were also enriched in multiple resistance pathways, including the EGFR tyrosine kinase inhibitor resistance pathway, suggesting that the immunosuppressive microenvironment is promoting or maintaining EGFR-TKI resistance." (PMID 40948762, 2025). "Additionally, a study combining CAR-T cells with radiotherapy to enhance anti-tumor efficacy against TNBC revealed that irradiating TNBC cells before co-culturing with EGFR-targeted CAR-T cells increased cytotoxicity." (PMID 40281554, 2025). "Cetuximab, an EGFR monoclonal antibody, enhanced the functions of pro-tumor M2 macrophages." (PMID 39994810, 2025). "In a mouse tumor model, as the tumors became resistant to erlotinib, αvβ3 integrin-negative HCC827 human EGFR-mutant lung tumors not only gained αvβ3 integrin but also became enriched for tumor-associated macrophages (TAMs)." (PMID 40243917, 2025). "For example, left- or right-sided tumor location may help guide the choice between anti-EGFR and anti-VEGF therapy." (PMID 41450739, 2025). "Thus far, anti-EGFR treatments have been disappointing largely due to tumor heterogeneity, redundant downstream signaling and an immune-suppressive tumor microenvironment in GBM9." (PMID 40678238, 2025). "It has been shown that persistent activation of the NF-κB pathway decreases sensitivity to anti-EGFR monoclonal antibodies and the continued activation of the pathway results in an inflammatory tumor microenvironment, which reduces the effectiveness of anti-EGFR monoclonal antibody treatment." (PMID 41305005, 2025). "Therefore, TCEs targeting EGFR face more severe on-target off-tumor toxicity, resulting in a limited therapeutic window." (PMID 40510353, 2025). "Combination therapy targeting FYN +IGF1 R and KDM4 +EGFR synergistically eliminates tumor in vivo." (PMID 40243589, 2025). "Overall, these findings indicated that B7H3/EGFR co-expression was highly prevalent in advanced NSCLC and correlated with poor survival and potentially impaired anti-tumor immunity, thereby underscoring the significance and promising clinical application of effective anti-EGFR/anti-B7H3 bsAbs." (PMID 41291854, 2025). "In this context, circulating tumor DNA (ctDNA) analysis offers a guideline-recommended non-invasive method to detect EGFR mutations." (PMID 40977812, 2025). "Hence, this molecular bridging function mediated by sAgrin possibly clusters Integrin β1 to EGFR in mechanosensitive adhesion sites in response to increased agrin with tumor stiffness." (PMID 40165020, 2025). "Interestingly, tumor cells with mutant EGFR exhibited enhanced tyrosine phosphorylation of MIG6 at Y394/Y395, resulting in increased binding between mutant EGFR and MIG6." (PMID 39948411, 2025). "In particular, integrins are known to mediate cell-ECM interactions and have been shown to play important roles in tumor progression, metastasis, anoikis resistance, and chemotherapy resistance through activation of downstream pathways such as the EGFR–AKT pathway." (PMID 41011230, 2025). "Thisstudy also identified that EGFR alterations could lead to tumor proliferationthrough ERK5-mediated nucleotide synthesis." (PMID 40518661, 2025). "The negative association suggests a complex interplay between EGFR-expressing tumor cells and ligand-expressing stromal cells." (PMID 39959305, 2025). "The activation of EGFR in tumor cells can modulate the expression of many genes in downstream signaling pathways to inhibit the migration, recognition, and killing of immune cells, thereby facilitating immune evasion by tumor cells and diminishing the efficacy of immunotherapy." (PMID 40859900, 2025).
tumor (continued). "Additionally, overexpression or mutation of EGFR enhances tumor cell proliferation, survival, and growth, while inactivation of PTEN removes constraints on tumor cell proliferation." (PMID 40075663, 2025). "CAF markers such as α-SMA, HGF, and podoplanin in tumor tissues could predict EGFR-TKI resistance.Targeting CAF-derived factors such as HGF or using antifibrotic agents may counteract TKI resistance." (PMID 40002883, 2025). "Notably, the expression levels of CMTM6 and EGFR within whole cells, on the cell membrane, and in the cytoplasm, all exhibited a significant elevation in tumor areas compared to the adjacent stromal tissue." (PMID 40521789, 2025). "The EGFR exon 19 deletion mutation was detected in the resected tumor, while the T790M mutation was absent." (PMID 40051929, 2025). "However, within the tumor microenvironment of EGFR-TKI-resistant cancers, TAMs tend to polarize toward the immunosuppressive M2 phenotype." (PMID 40003951, 2025). "Additionally, hsa-miR-125b and hsa-miR-155 are related to tumor staging, invasion degree, and EGFR expression, potentially playing a role not only in prognostic evaluation but also in guiding EGFR-targeted therapy." (PMID 41002349, 2025). "Specifically, the median overall survival was 10 months for patients treated with chemotherapy alone versus 13 months for patients treated with chemotherapy plus ICI in patients whose tumor transformed after developing resistance to EGFR-TKI therapy (Hazard ratio 0.75, 0.36−1.56)." (PMID 41001033, 2025). "As the high expression of PCSK9 can activate HER3/EGFR to promote tumor growth and metastasis, therefore reducing PCSK9 level may be a good strategy for treating TNBC." (PMID 40192514, 2025). "Additionally, tumor cells exploit PD-L1 to suppress T cell recognition, while aberrant EGFR signaling and cell cycle dysregulation promote cell proliferation." (PMID 40895068, 2025). "In another study, engineered EVs modified with GE11 peptides selectively targeted EGFR-positive tumor cells and delivered Dox, showing higher targeting efficiency, increased apoptosis, and reduced cytotoxicity to normal cells compared to non-modified EVs and free Dox treatments." (PMID 40317075, 2025). "Moreover, MES influences the EGFR and PPARγ pathways, as well as the cell cycle, ultimately leading to tumor growth inhibition." (PMID 40699726, 2025). "They found that [18F]FP-Lys-Pep4 could specifically bind to EGFR-positive tumor cells and clearly delineate the tumor morphology in PET imaging." (PMID 40906195, 2025). "Given that USP11 appears to play a functional role in EGFR- or TLR-driven CRC progression, we investigated whether USP11 could be a viable therapeutic target for inhibiting EGFR- or TLR-driven CRC tumor growth." (PMID 41419456, 2025). "We undertook an unbiased approach to correlate somatic alteration status (mutation or copy number alterations) with TIL infiltration and found – tumours with low‐TIL are significantly (p = .007) more enriched with EGFR copy number amplification (71.4%) as compared with tumours with high‐TIL (0%)." (PMID 40621643, 2025). "Besides their targeting abilities, mAbs are also known for inhibiting tumor cell proliferation or angiogenesis by binding specifically to cell surface receptors that are unique or overexpressed by tumor cells, such as EGFR." (PMID 39940134, 2025). "By elucidating the role of circ-EGFR in modulating tumor response to cetuximab via the circ-EGFR/miR-942-3p/GAS1/Hh regulatory axis, our findings provide key molecular insights into the biologic changes associated with varying responses to anti-EGFR therapy in CRC." (PMID 41214390, 2025).
tumor (continued). "While anti-EGFR treatments target the EGFR pathway to inhibit tumor growth, NRAS mutations can activate downstream signaling pathways independently of EGFR, allowing tumor cells to evade EGFR blockade and continue proliferating." (PMID 40526090, 2025). "EGFR on tumor cells can be identified using molecular recognition elements (MoREs)." (PMID 40943631, 2025). "Given the role of EVs in transferring oncogenic signals, reducing p-EGFR packaging into EVs may limit the ability of tumor-derived EVs to propagate EGFR-driven signaling, potentially contributing to the therapeutic effects of TKIs." (PMID 40210802, 2025). "In line with this hypothesis, the depletion of PCBP2 notably abolished the EGFR-driven tumor angiogenesis in vivo." (PMID 39816681, 2025). "Several studies have investigated potential tissue-based biomarkers for predicting progression-free survival (PFS) in mCRC, including tumor DNA mutations, Consensus molecular subtypes (CMS), and molecular alterations linked to the EGFR pathway." (PMID 41214390, 2025). "Binding to respective tumor cell-associated antigen (TAA) was assessed by incubating supernatants containing BICA on EGFR/MICA-positive or -negative cell lines." (PMID 40741595, 2025). "Importantly, treatment with 10 μM PYCR1-IN-1 significantly reduced the size of EGFR- or TLR-induced tumor spheroids in H1299, H460, A549, H358 cells compared with cells treated with EGF or TLR agonists alone." (PMID 41254241, 2025). "Future research on the sustained active expression or inhibition of IFI6 and similar downstream molecules associated with HSP90AA1 in EGFR mutant LUAD and other cancer subtypes is also crucial for advancing our understanding of tumor stress responses and resistance." (PMID 40234395, 2025). "Blocking EGFR might reshape the tumor microenvironment, enhancing NK cell function through cytokine release (e.g., IL-12, IL-15) and interferon-gamma." (PMID 40869384, 2025). "Moreover, EGFR can modulate tumor angiogenesis by influencing the levels of factors such as angiopoietin-1 (Ang-1) and vascular endothelial growth factor (VEGF), consequently affecting the high invasiveness and metastatic potential of tumors." (PMID 40732366, 2025). "It has been found that IRSp53 is tyrosine phosphorylated at multiple sites in response to EGFR stimulation, and knocking down of IRSp53 diminished cell proliferation in cells that v-Src transformed and tumor formation in mice through p-AKT/p-Stat3/cyclin D1 signaling pathway." (PMID 41200137, 2025). "In this context, our rat PVL model provides translational insight into how hepatic hypertrophy may modulate tumor behavior under EGFR inhibition, helping to interpret why perioperative cetuximab could yield unexpected oncological outcomes in clinical practice." (PMID 41454126, 2025). "In kinase-addicted NSCLC, a reduction in tumor cell survival following EGFR- and ALK-directed therapy interventions could be counteracted by exposure to nonmalignant CAF populations or CAF-associated paracrine mediators." (PMID 40524253, 2025). "However, EGFR inhibitors have not shown clinical efficacy in contrast to other EGFR-driven neoplasms due to the unique EGFR biology found in GBM." (PMID 40581663, 2025). "Additionally, Patritumab deruxtecan (HER3-DXd)—a HER3 antibody drug—is also currently undergoing testing in a phase 2 clinical trial for patients with tumor progression after EGFR TKI therapy." (PMID 40943615, 2025). "Similarly, in our collected tumor tissues, we observed high expression levels of SYVN1 and EGFR in tumor tissues and a positive correlation between their expression." (PMID 40877231, 2025). "The association of EGFR with the concerning phenotype of CPI-induced hyper-progression characterised by accelerated tumour growth and clinical deterioration indicates further caution for the use of CPIs in EGFR-driven tumours, including ESCCs." (PMID 40615716, 2025).
tumor (continued). "Importantly, utilizing LUAD patient‐derived organoid and xenograft models, it is demonstrated that targeting RAC1B potently suppresses tumor growth and enhances the efficacy of EGFR inhibitors." (PMID 40548642, 2025). "Concurrent preclinical studies confirmed the limited impact on 18F-FDG uptake in EGFR-altered GBM tumor, suggesting this limitation may be due to inability of the EGFR TKI to robustly inhibit extracellular domain mutant EGFR signaling in GBM." (PMID 40051661, 2025). "Consequently, targeting STAT3 inhibition or employing anti-CD47 monoclonal antibodies can enhance TAM-mediated phagocytosis of tumor cells, thereby mitigating EGFR-TKI resistance." (PMID 40003951, 2025). "The present study aimed to better understand how constitutive activation of EGFR influences the release of EVs and their miRNA cargo composition, which could offer insight into tumor progression and potential therapeutic targets." (PMID 40210802, 2025). "This acquisition may lead to increased mutant allele transcription and EGFR gene activity under EGFR‐TKI treatment pressure, manifesting as pronounced genome instability and genome‐wide hypomethylation, ultimately affecting tumor cell sensitivity to EGFR‐TKI." (PMID 39741120, 2025). "Additionally, the fluorescently labeled scFv‐SNAP‐tag immunoconjugates have demonstrated their capacity to profile South African TNBC tumor biopsies for clinically relevant EGFR, CSPG4, and CD44 biomarker expression." (PMID 40970572, 2025). "EGFR amplification and PTEN loss play critical roles in ovarian cancer progression by regulating key signaling pathways involved in cell proliferation, survival, and tumor growth by enhancing downstream signaling pathways such as PI3K-AKT." (PMID 39936963, 2025). "GCC2 promoted tumour growth by modulating vesicle trafficking of EGFR to the nucleus." (PMID 40293576, 2025). "Additionally, it reduces EGFR promoter activity.In vivo, the combination significantly suppresses tumor growth andoutperforms the standard Dox and cyclophosphamide regimen in inhibitingmetastasis." (PMID 40032551, 2025). "This review provides a comprehensive synthesis of current knowledge on the clinical utility of EGFR molecular analysis in ctDNA, alongside its relationship with other circulating biomarkers widely implemented in clinical laboratories, such as serum tumor markers (STMs)." (PMID 40977812, 2025). "Additionally, in xenograft models established by subcutaneous implantation of either PC9-parental or EGFR-E804K knock-in cells, the tumor growth and weight of EGFR-E804K knock-in xenografts were significantly reduced." (PMID 40259053, 2025). "By competitively inhibiting EGFR activation, cetuximab effectively blocks signal transduction pathways mediated by endogenous ligands, resulting in the suppression of tumor cell proliferation, inhibition of tumor angiogenesis and metastasis, and induction of apoptosis in malignant cells." (PMID 40777125, 2025). "This case preserved EGFR exon-19 deletion on the tumor progression specimen." (PMID 41226501, 2025). "In addition, TAVO412 was shown to have stronger anti-tumor activities in combination with other standards of care treatments that included radiotherapy, chemotherapy, and 3rd generation EGFR TKIs." (PMID 40452841, 2025). "A deeper understanding of tumor heterogeneity and the identification of specific resistance mechanisms might help to overcome EGFR‐TKI resistance." (PMID 40842076, 2025). "Furthermore, probiotics can inhibit the epidermal growth factor receptor (EGFR) signaling pathway to eradicate tumor development, while they can also trigger autophagy to mitigate inflammation and counteract GI malignancy." (PMID 40869174, 2025). "Given the metabolic role of SLC16A3 in maintaining redox homeostasis, its inhibition could sensitize tumor cells to ferroptosis under EGFR-TKI treatment." (PMID 41293164, 2025).
tumor (continued). "Notably, these compounds were shown to resensitize resistant NSCLC cells to EGFR-TKIs, with 10k inhibiting tumor growth and enhancing Osimertinib efficacy in resistant xenografts." (PMID 41281943, 2025). "However, the efficacy of ICIs remains to be fully evaluated in the relatively small subpopulation of patients whose tumor has transformed to SCLC after developing resistance to EGFR-TKIs." (PMID 41001033, 2025). "Activation of EGFR in GBM promotes tumor development via multiple critical downstream pathways." (PMID 40332008, 2025). "This stabilization leads to enhanced EGFR signaling, contributing to tumor growth and resistance." (PMID 40877231, 2025). "These preclinical data suggest that changes in FDG uptake could serve as a surrogate marker for tumor pharmacodynamics in response to EGFR TKI therapy." (PMID 40051661, 2025). "Intriguingly, although similar degrees of EGFR dimerization and levels of EGFR phosphorylation were observed in all tumor cell lines within the first 6 h of exposure to hypoxia, the level of pEGFR did not remain constant in these cells during the subsequent 48-h observation period." (PMID 40940319, 2025). "For example, 80% of metastatic lung cancer patients with EGFR-activating mutations (EGFRmut) initially respond to osimertinib, a third-generation EGFR-targeting drug; yet, almost all experience tumor progression within 2 years, with a median duration of response of 17 months." (PMID 39699269, 2025). "In addition to its ability to block both EGFR- and cMET-mediated downstream signaling, the antibody exerts its anti-tumor effects through various Fc-mediated mechanisms, such as ADCC and ACDP." (PMID 40510353, 2025). "Through this analysis, the researchers validated the impact of AuNPs (0.45 mmol) on EGFR downstream signaling pathways over time, and found that AuNPs gradually diminish EGFR activation, which results in inactivation of downstream players leads to tumor suppression." (PMID 40432717, 2025). "Next, we aimed to determine whether circ-EGFR could serve as a reliable predictor of cetuximab response by evaluating the correlation between circ-EGFR and maximum tumor shrinkage (MTS), a key indicator of treatment response." (PMID 41214390, 2025). "To investigate whether EGFR expression in CRCs exhibits the same heterogeneity as in clinical specimens, we assessed the expression and localization of EGFR in various CRC tumor cell lines using IF staining." (PMID 39560161, 2025). "EGFR is a tyrosine kinase receptor critical for tumor cell proliferation and survival." (PMID 40135231, 2025). "Furthermore, EGFR protein overexpression was independently correlated with aggressive tumor features, including poor differentiation and nodal metastasis with extracapsular spread." (PMID 40699851, 2025). "Thus, our study aimed to evaluate RKIP's impact on tumor aggressiveness and EGFR‐targeted therapy efficacy in NSCLC." (PMID 40720248, 2025). "This may be attributed to EGFR’s low-level expression in normal tissues, which constrains dosing due to on-target/off-tumor risks, and to the immunosuppressive TME, including PD-L1 expression and T-cell exhaustion, which limit CAR-T expansion and activity." (PMID 40904467, 2025). "To assess this in a scenario that mimics EGFR‐addicted tumor‐thriving conditions, we silenced agrin in both wild‐type and mutant EGFR (del 19) overexpressing H1299 and implanted them subcutaneously with soft (≈0.5 kPa) or stiff VitroGel RGD (30 kPa) in SCID mice." (PMID 40165020, 2025). "Fueling this caveat is a binary problem whereby i) the identities of ECM protein(s) that mechanosensitize EGFR toward tumor stiffness remain elusive; and ii) the functional regulatory pathway of EGFR on these ECM proteins that crosstalk with tumor‐mechanotransduction network is not well defined." (PMID 40165020, 2025).